MAP7 (microtubule associated protein 7)
Diseases named in the same sentence as MAP7 in open-access papers (continued):
Sharing a sentence is not in itself a finding about the gene and the disease.
tumor (15 papers, 2011 to 2025). "MAP7 has been shown to affect the migration, cell cycle, and drug resistance of various tumor cells." (PMID 38726137, 2024). "To further prove the promoting effect of MAP7 on CC that we observed in vitro, we next detected the influence of MAP7 on tumor growth in vivo." (PMID 32760221, 2020). "Moreover, the expression of MAP7 was negatively correlated with CBX1 expression in tumor tissues from a subcutaneous xenograft mouse model." (PMID 36310139, 2022). "Hence, lots efforts are still required in the future to achieve a comprehensive understanding on the molecular mechanism of MAP7 in tumor progression." (PMID 32760221, 2020). "In vivo tumorigenicity assay was performed to explore the influence of MAP7 on tumor growth." (PMID 32760221, 2020). "In our study, the MAP7-associated microRNA profile revealed that in MAP7high CN-AML patients, some oncogenic microRNAs such as miR-196b and miR-99a were up-regulated, whereas anti-tumor microRNAs such as miR-193a and miR-27a were down-regulated." (PMID 27686215, 2016). "Since E6, E7, MAP7 and LTF are also related to tumor cell apoptosis, we used flow cytometry to further evaluate SiHa cell apoptosis after treatment with CLD." (PMID 37344615, 2023). "The protein levels of HPA demonstrated that MAP7 and SLC27A2 levels were lower, and SLC3A1 levels were higher, in tumor tissues than in normal samples, in accordance with the results of the TCGA-KIRC and RT-PCR." (PMID 36620592, 2022). "qPCR experiments verified that the expressions of MAP7, CDK1, PPP3R1, PRKC1, CCND1 and HDAC1 genes were indeed altered in AT/RT tumor tissue." (PMID 35524230, 2022). "The expressions of several drug-resistant genes including MDR1, GAGE, STAT1, and MAP7 were found to be overexpressed in three Pyk2 overexpressing HCC cell lines and in tumor liver tissues of HCC patients." (PMID 22096562, 2011). "Pyk2, MDR1, GAGE1, MAP7 and STAT1 were found to be overexpressed in more than 60% of the tumor liver tissues compared to the adjacent non-tumor liver tissues (*p<0.05)." (PMID 22096562, 2011). "We next scanned the TCGA database and found that MAP7 was upregulated in tumour and negative correlated with OS and DFS." (PMID 31956295, 2020).
cancer (13 papers, 2013 to 2024). A tumor composed of atypical neoplastic, often pleomorphic cells that invade other tissues. "Research on MAP7 (Microtubule-associated protein 7) is shedding light on its pivotal role in cancer progression and drug resistance." (PMID 38726137, 2024). "Microtubule-associated protein 7 (MAP7) plays an important role in cancer cells." (PMID 27686215, 2016). "Functionally, the inhibition of MAP7 suppresses cancer cell proliferation, migration, and invasion while promoting apoptosis." (PMID 38726137, 2024). "By suppressing such miRNAs, circ_NEK9 and circ_NHSL1 elevate the expression of microtubule-associated protein 7 (MAP7) and tyrosine 3-monooxygenase/tryptophan 5-monooxygenase activation protein zeta (YWHAZ), respectively, in cancer cells." (PMID 35055115, 2022). "The metastatic ability of cancer cells is intensified by plasma exosomes, connoting the contribution of exosomal circ_NEK9 to gastric cancer progression by raising MAP7 levels." (PMID 35055115, 2022). "Several studies had reported MAP7 involved in cell cycle progression and autophagy pathway in cancers." (PMID 36620592, 2022). "The expression level of MAP7 in CC tissues and normal tissues were analyzed using the data obtained from The cancer genomes atlas (TCGA) and genotype-tissue expression (GTEx) databases." (PMID 32760221, 2020). "Further specific mechanism MAP7 on cancer cell was still needed to make it an ideal therapeutic target." (PMID 31956295, 2020). "In summary, the present study identifies several novel miR-16 targets and illustrates a novel function of miR-16 targeting MAP7 in modulating proliferation in cancer cells." (PMID 23941513, 2013). "Additional studies are necessary to uncover the clinical effects of miR-16 in regulating MAP7 during cancer progression." (PMID 23941513, 2013). "Additional studies are necessary to fully elucidate the exact roles of miR-16 in regulating MAP7 in other cancer cells." (PMID 23941513, 2013). "We further experimentally validated MAP7 as a direct target of miR-16 and demonstrated that this targeting plays a critical role in regulating proliferation in cancer cells." (PMID 23941513, 2013). "Moreover, MAP7 enhances OC cell proliferation and migration in vitro, consistent with observations in other cancer types." (PMID 38726137, 2024). "MAP7 was reported to be upregulated and correlated with the prognosis of cancers." (PMID 31956295, 2020). "There is little known about the role of MAP7 with respect to cancer progression." (PMID 31701684, 2020). "To date, the function of MAP7 in cancer development has not been fully understood." (PMID 32760221, 2020). "Collectively, MAP7 might play a promoting role in cancer cell growth and motility and exert a repressive role in cell apoptosis, which were consistent with the previous speculation that MAP7 was a promoter in cancer progression." (PMID 32760221, 2020). "The modulation of MAP7 protein level by miR-16 may explain, at least in part, why the downregulation of miR-16 can promote cancer progression." (PMID 23941513, 2013). "Therefore, the downregulation of miR-16 in cancer cells would, in theory, relieve the suppression of miR-16 on MAP7, which in turn accelerates tumorigenesis." (PMID 23941513, 2013). "The potential function and mechanism of MAP7 in cancer was still unknown." (PMID 31956295, 2020). "Furthermore, the role of MAP7 in cancer progression is also unclear." (PMID 23941513, 2013). "Our study unveils, for the first time, the pairwise interactions among MAP7, β-catenin, and CBY1, shedding light on their dynamic equilibrium and signaling within cells and offering avenues for novel cancer treatment strategies targeting these interactions." (PMID 38726137, 2024). "mRNA levels for the cancer progression-related genes HPV16-E6, HPV16-E7, IL6, and MAP7 were significantly downregulated in SiHa cells treated with CLD compared to control cells, while LTF was upregulated." (PMID 37344615, 2023).
cancer (continued). "Finally, RT-PCR showed that MAP7, SLC16A12, and SLC27A2 decreased, while SLC3A1 increased, in cancer cells." (PMID 36620592, 2022). "Finally, we demonstrated that miR-16 targeting MAP7 played a critical role in regulating proliferation but not apoptosis and cell cycle progression in cancer cells." (PMID 23941513, 2013). "Although we did not investigate the consequence of miR-16 targeting MAP7 in other cancer cell lines, as miR-16 could regulate the expression of MAP7 in A549, HeLa and MCF-7 cells, we speculate that miR-16 might have similar cellular functions through silencing MAP7." (PMID 23941513, 2013).
MAP7 also shares sentences with these, for which no sentence is quoted: leukemia (2 papers); lung carcinoma (2); deafness (1); multiple sclerosis (1); non-small cell lung carcinoma (1); Ovarian cyst (1); prostate carcinoma (1); serous ovarian cancer (1).